IL1R2 (interleukin 1 receptor type 2)
Description:
Non-signaling receptor for IL1A, IL1B and IL1RN. Reduces IL1B activities. Serves as a decoy receptor by competitive binding to IL1B and preventing its binding to IL1R1. Also modulates cellular response through non-signaling association with IL1RAP after binding to IL1B. IL1R2 (membrane and secreted forms) preferentially binds IL1B and poorly IL1A and IL1RN. The secreted IL1R2 recruits secreted IL1RAP with high affinity; this complex formation may be the dominant mechanism for neutralization of IL1B by secreted/soluble receptors.
Synonyms: IL-1R-2; IL-1RT-2; IL-1RT2; CD121b; IL1RB; CDw121b; IL1R2c
Tractability: Antibody: UniProt places it where antibodies can reach, with high confidence; its Gene Ontology location is reachable by antibodies, with high confidence; UniProt predicts a signal peptide or a membrane-spanning region.
Gene: Protein-coding gene on chromosome 2 (101,991,824 to 102,029,018, forward strand). Ensembl gene ENSG00000115590.
Subcellular location: Secreted (Isoform Short); Cell membrane (Isoform Long)
Pathways (Reactome):
Immune System: Interleukin-1 signaling; Interleukin-10 signaling
Gene Ontology:
Molecular function: protein binding; interleukin-1 receptor activity; interleukin-1 binding; interleukin-1, type II, blocking receptor activity
Biological process: cell surface receptor signaling pathway; immune response; monocyte differentiation; negative regulation of inflammatory response; negative regulation of interleukin-1 alpha production; negative regulation of interleukin-1 beta production; negative regulation of interleukin-1-mediated signaling pathway; cytokine-mediated signaling pathway
Cellular component: interleukin-1 receptor complex; cell surface; plasma membrane; cytoplasm; extracellular region
Genetic constraint (gnomAD): Loss-of-function variants: 33 observed, 31.81 expected, observed/expected ratio (o/e) 1.04, 90% interval 0.79 to 1.39. The upper end of that interval is the gene's LOEUF score, 1.39, which puts it in group 5 of 6, group 1 being the genes least tolerant of losing a copy. Missense variants: 459 observed, 457.75 expected, observed/expected ratio (o/e) 1, 90% interval 0.93 to 1.08. Synonymous variants: 188 observed, 179.66 expected, observed/expected ratio (o/e) 1.05, 90% interval 0.93 to 1.18.
Homologues: Orthologues: chimpanzee IL1R2 (99% identical), macaque IL1R2 (95% identical), dog IL1R2 (72% identical), rabbit IL1R2 (72% identical), pig IL1R2 (69% identical), rat Il1r2 (62% identical), mouse Il1r2 (61% identical), guinea pig IL1R2 (57% identical), tropical clawed frog il1r2 (35% identical). Paralogues in human: IL1RAPL2 (27% identical), IL1RAPL1 (24% identical), IL1R1 (23% identical), IL1RL2 (22% identical), IL1RAP (19% identical), IL18RAP (18% identical), IL1RL1 (17% identical), IL18R1 (17% identical), LAG3 (16% identical), SIGIRR (7% identical).
Diseases named in the same sentence as IL1R2 in open-access papers:
IL1R2 is named in the same sentence as 157 diseases in open-access papers, as found by Europe PMC text mining. Sharing a sentence is not in itself a finding about the gene and the disease. The quoted sentences say what the papers report.
Sepsis (40 papers, 2014 to 2026). Sepsis is defined as life-threatening organ dysfunction caused by a dysregulated host response to infection. "Network topology analysis indicated that numerous hub genes belong to a closely interconnected module governed by IL1R2 signaling, a mechanism increasingly associated with immunological dysregulation in sepsis." (PMID 40699828, 2025). "IL1R2, which encodes CD121b, was identified as one of the genes most closely correlated with sepsis progression." (PMID 40230851, 2025). "IL1R2-deficient mice exhibited heightened susceptibility to sepsis, with increased inflammation, organ injury, and mortality." (PMID 40704655, 2025). "Expression of CD247, IL-2Rβ and TGF-βR3 was positively associated with the survival in patients with sepsis, and expression of IL-1R2 was negatively associated (p < 0.05)." (PMID 36855106, 2023). "A recent study used single cell RNA sequencing to reveal a CD14+ monocyte phenotype named MS1, characterized by high expression of RETN, ALOX5AP, and IL1R2, that was unique in patients with sepsis and associated with sepsis-induced immunosuppression." (PMID 36470832, 2022). "Similarly, in another study, IL-1R2+ immature neutrophils from patients with sepsis were associated with more severe disease and a higher risk of early mortality." (PMID 39028622, 2024). "Besides, IL1R2, a decoy receptor for IL-1, has been implicated in sepsis." (PMID 36532037, 2022). "Our study provides a comprehensive analysis of IL-1R1 and IL-1R2 expression across different cell populations and organs during sepsis by analyzing published sc-RNAseq data and flow cytometry." (PMID 41293423, 2025). "We reveal distinct and compartmentalized expression landscapes for IL-1R1 and IL-1R2 across organs during sepsis." (PMID 41293423, 2025). "Specifically, following sepsis, F4/80hi macrophages polarize toward an anti-inflammatory phenotype and exhibit elevated expression of anti-inflammatory genes such as Socs3, Il1r2, and Il1rn." (PMID 41465886, 2025). "In severe infections and sepsis, patient subsets with poor outcomes present increased numbers of circulating IL-1R2+ immature neutrophils, which possess immunosuppressive properties." (PMID 41087719, 2025). "We identified a pivotal role of Interleukin-1 receptor 2 (IL-1R2) in modulating inflammatory responses in sepsis, with IL-1R2 showing a 2.1-fold upregulation in septic patients." (PMID 40699828, 2025). "These pathways collectively underscore the immune dysregulation seen in sepsis, suggesting that IL1R2 plays a central regulatory role." (PMID 40699828, 2025). "Further, it emphasized the central role of NF-κB/NLRP3 signaling pathway is in sepsis and how IL-1R2-mediated inhibition of this axis leads to the decrease in recruitment and activation of effector cells of immune system." (PMID 40699828, 2025). "In conclusion, this study helps us advance our understanding of sepsis pathophysiology by highlighting IL-1R2 as an important regulator of inflammation and immune suppression." (PMID 40699828, 2025). "Flow cytometry also confirmed that the resident tissue macrophages, kupffer cells, in the liver maintained low levels of IL-1R2 expression even during sepsis, comparable to their expression levels in sham mice." (PMID 41293423, 2025). "To investigate the expression and significance of IL-1R2 in sepsis, we conducted high-dimensional flow cytometry of circulating cells from patients stratified according to the Sequential Sepsis-Related Organ Failure Assessment (SOFA) score." (PMID 40204720, 2025). "Sepsis induced a significant upregulation of IL-1R2 on neutrophils and monocyte-derived macrophages across all organs." (PMID 41293423, 2025). "To investigate the roles of IL-1R subtypes, specifically IL-1R1 and IL-1R2, in sepsis, we utilized single-cell RNA sequencing (scRNA-seq) and flow cytometry to comprehensively map their expression profiles across various immune cell populations and organs." (PMID 41293423, 2025).
Sepsis (continued). "In this study, the objective is to investigate the regulatory role of IL-1R2 as a potential biomarker for sepsis and its connection to key inflammatory pathways, including the IL-6/JAK/STAT3 axis." (PMID 40699828, 2025). "The study was performed to find evidence to establish the role of IL1R2 in controlling the immune response during sepsis." (PMID 40699828, 2025). "The aim of future research should be to create IL-1R2-focused treatments, learn more about the complex molecular networks involved in sepsis, and investigate novel approaches to help individuals with the illness regain their immune systems." (PMID 40699828, 2025). "and identified a pivotal role of Interleukin-1 receptor 2 (IL-1R2) in modulating inflammatory responses in sepsis." (PMID 40699828, 2025). "Sepsis patients exhibited a distinct pattern, with decreased sIL-1R1 plasma concentrations but markedly increased levels of IL-1R2 and IL-1R1." (PMID 40699828, 2025). "This is consistent with previous studies showing that IL-1R2 is protective in various inflammatory disease models, including models of sepsis, and sterile inflammation." (PMID 41293423, 2025). "This distinction raises important questions regarding the differential roles of IL-1R1 and IL-1R2 in innate immunity and inflammation during sepsis." (PMID 41293423, 2025). "Consistent with the scRNA-seq data, flow cytometry confirmed that IL-1R2 was significantly upregulated on neutrophils and monocytes derived macrophages in the lung during sepsis." (PMID 41293423, 2025). "For example, IL1R2 is a blood biomarker of several inflammatory diseases such as Dengue, sepsis, and rheumatoid arthritis, but the relationship between circulating levels and disease prognosis or severity is variable." (PMID 40517318, 2025). "In the sepsis group, FCGR1A and TLR5 were positively associated with survival compared to ELANE, IL1R2, RAB13, and RNASE3, which were adversely associated with survival." (PMID 39655195, 2024). "Six core genes, ELANE, IL1R2, RAB13, RNASE3, FCGR1A, and TLR5, have been linked to sepsis prognosis." (PMID 39655195, 2024). "Meta-random-effects model analysis showed that elevated expression levels of ELANE, FCGR1A, IL1R2, and RNASE3 were associated with sepsis." (PMID 39655195, 2024). "IL1R2 was also upregulated in human neonates with bacterial infection and infants with late-onset sepsis." (PMID 39057983, 2024). "In vitro experiment was performed to test expression of CD247, IL-2Rβ, TGF-βR3 and IL-1R2 in human THP-1 cells of sepsis." (PMID 36855106, 2023). "The analysis, comprising 26 sepsis patients, showed that an IL1R2+ neutrophil state was expanded in a transcriptomic sepsis endotype." (PMID 37317092, 2023). "When comparing the sepsis patients with normal individuals, IL-1R2 was up-regulated while IL-2Rβ and TGF-βR3 were down-regulated." (PMID 36855106, 2023). "In the current study, RT-qPCR was performed to show differential high expression of IL-1R2 in sepsis, which was statistically different with that in healthy people (p = 0.001), consistent with the RNA-seq analysis." (PMID 36855106, 2023). "By mimicking sepsis-induced myelopoiesis, it was shown that IL-1R2+ monocytes originate from bone marrow mononuclear cells differentiated/activated by pathogen associated molecular patterns (PAMPs)." (PMID 35211118, 2022). "As described in sepsis, HLA-DRlow IL-1R2+ cells showed impaired activation upon stimulation with LPS, suggesting that monocytes underwent function exhaustion as a consequence of the viral infection." (PMID 35211118, 2022). "Using a meta-analysis and network-based approach on samples of sepsis and normal healthy controls, we identified the key genes for inflammation in sepsis with increased expression of IL1R2 and ARG1, as indicated by semiquantitative-PCR studies." (PMID 31817302, 2019).
Sepsis (continued). "Recently, increased IL-1R2 expression has been noted in septic patients compared with controls, and IL-1R2 has been proposed as a new biomarker for sepsis diagnosis." (PMID 30463588, 2018). "IL1R2 expression has been suggested to be a marker of sepsis and high circulating IL1R2 protein levels have been reported in critically-ill patients with sepsis." (PMID 24612859, 2014). "As a bait receptor for IL-1β, IL-1R2 has a two-fold function in the pathophysiology of sepsis." (PMID 40699828, 2025). "In addition, flow cytometry confirmed that IL-1R2 protein were significantly upregulated on neutrophils in the blood during sepsis." (PMID 41293423, 2025). "In addition, the TNF-α/NF-κB pathway, a major inflammatory driver in sepsis, is modulated by IL-1R2 activity." (PMID 40699828, 2025). "And IL-1R2 protein was significantly increased on monocytes in the blood during sepsis." (PMID 41293423, 2025). "While interleukin 1 receptor 2 (IL1R2) acts as a decoy receptor for IL1α/β, its potential impact on cell metabolism and death during sepsis remains unclear." (PMID 40704655, 2025). "In addition, IL-1R2 expression is minimal in cluster 1 and 3 under health and sepsis condition, which co-expressed with Fcgr1and Tim4 but lack of Cxcr2, identified as resident tissue macrophages in the heart." (PMID 41293423, 2025). "Differentially expressed genes between 28-day survivors and non-survivors include transcripts previously linked to sepsis outcomes such as IL1R2, OLAH, and CX3CR1 6,41." (PMID 38890515, 2024). "IL1R2 is elevated in sepsis and correlates with disease severity." (PMID 35957694, 2022). "This further indicates that inflammasome assembly, IL-1 or IL1R2, macrophage polarization, and the neutrophil recruitment process could be viable drug targets for the treatment of sepsis." (PMID 31817302, 2019). "Supporting the significance of the inflammasome in sepsis survivors, they also exhibited increased expression of genes downstream from inflammasome activation including interleukin-1 receptor 2 (IL1R2), IL18R1, and the IL-18 receptor accessory protein (IL18RAP)." (PMID 25538794, 2014). "During sepsis, the bone marrow releases a large amount of immature granulocyte (IGs) through emergency granulopoiesis, such as CEACAM8+Neu, S100A8/9hiNeu, IL1R2+Neu, PADI4+Neu, MPO+Neu and cycling MK167+CYP1B1+Neu." (PMID 40356926, 2025). "GeneWalk analysis identified potential regulatory genes involved in sepsis, including IL1B, CDKN1A, CDK2, CSF3, and IL1R2, which were included among the SRGs." (PMID 40303348, 2025). "Despite the marked upregulation of IL-1R2 on recruited myeloid cells, we observed that alveolar macrophages in the lung tissue maintained low levels of IL1R2 expression even during sepsis, comparable to their expression levels in healthy conditions." (PMID 41293423, 2025). "Analysis of clinical prognostic data (dataset: GSE65682) in the context of sepsis revealed that the upregulation of ELANE, IL1R2, RAB13, and RNASE3 affected prognosis by reducing the survival rate of patients with sepsis." (PMID 39655195, 2024). "ELANE, IL1R2, RAB13, and RNASE3 promote cell death, whereas FCGR1A and TLR5 facilitate cell survival in sepsis." (PMID 39655195, 2024). "When comparing the sepsis patients with SIRS cases, CD247, IL-2Rβ and TGF-βR3 were down-regulated significantly but IL-1R2 marginally varied." (PMID 36855106, 2023). "In vitro cellular experiment showed up-regulated expression of IL-1R2 while down-regulated of CD247, IL-2Rβ, TGF-βR3 in sepsis patients." (PMID 36855106, 2023). "This study identified four core genes, including CD247, IL-1R2, IL-2Rβ and TGF-βR3, with potential to be novel biomarkers for the prognosis of sepsis." (PMID 36855106, 2023). "A scRNA-sequencing study of urinary-tract infection (UTI) patients identified IL-1R2 as one of the markers of a subset of CD14+, HLA-DRlow monocytes, which expand in different sepsis cohorts." (PMID 35211118, 2022).
Sepsis (continued). "This study demonstrates the role of significant and widespread immune activation (IL1R2, MMP9), along with oxidative stress (ARG1) and the recruitment of neutrophils, in sepsis (ELANE, MPO)." (PMID 31817302, 2019). "The DEGs (IL1R2, ARG1, FCGR1A, MMP9, ELANE, and MPO) that were common on day1 and day3 of sepsis, with at least 2.0-fold upregulation, were selected for constructing and visualizing the PPI network using Cytoscape." (PMID 31817302, 2019). "Importantly, our findings indicate that high expression levels of ELANE, IL1R2, RAB13, and RNASE3 promote death rates in sepsis, whereas high expression levels of FCGR1A and TLR5 improve the survival rate of patients with sepsis." (PMID 39655195, 2024). "S1PR5, GNLY, CD247, KLRG1, IL-1R2, AUTS2, IL-2Rβ, ARG1, TGFBR3, TLR5 and PRF1 in the top 80 genes in the two modules were located toward the center of the co-expression network, and CD247, IL-2Rβ, TGF-βR3 and IL-1R2 were identified as core genes in sepsis." (PMID 36855106, 2023). "Collectively, the elevation of immuno-suppressors such as PD-L1, SLPI and IL-1R2 and reduction of co-stimulatory molecules such as CD86 contribute to the immuno-suppressive phenotype characteristics of exhausted monocytes observed in clinical sepsis patients." (PMID 34777396, 2021). "For example, IL1R2 and SOCS3 were reported to drive the neonatal innate immune response to sepsis." (PMID 32908583, 2020). "The results of our study indicate that upregulated IL1R2 and ARG1 may be further correlated with the key role of inflammasome in sepsis." (PMID 31817302, 2019). "In addition, the observed up-regulation of (counter-) receptors of interleukin-1 and -18 (IL1R2, IL18R, IL18RAP), still holds true when comparing patients with sepsis to healthy controls." (PMID 29920518, 2018). "In summary, these findings suggest that ELANE, IL1R2, RAB13, RNASE3, FCGR1A, and TLR5 may influence the prognosis of patients with sepsis and provide novel insights and potential avenues for the treatment of sepsis." (PMID 39655195, 2024). "Another study demonstrated that a higher interleukin-1 receptor 2 (IL1R2) level could be potentially a new biomarker for G- sepsis versus G+ sepsis, while no deep investigation was carried out." (PMID 36703970, 2022). "In addition, IL-1R2 expression is minimal in cluster 9, which co-expressed Adgre1, Clec4f and Tim4 and identified as resident macrophages, namely Kupffer cells in the liver, and this expression did not increase in response to sepsis." (PMID 41293423, 2025). "Finally, the expression of the topmost upregulated genes (ARG1, IL1R2, ELANE, MMP9) was quantified by reverse transcriptase-PCR (RT-PCR), and myeloperoxidase (MPO) expression was confirmed by immunohistochemistry (IHC) staining in the lungs of a well-established sepsis mouse model." (PMID 31817302, 2019).